CHEK2 (checkpoint kinase 2)
Diseases named in the same sentence as CHEK2 in open-access papers (continued):
Sharing a sentence is not in itself a finding about the gene and the disease.
prostate carcinoma (continued). "We have previously demonstrated that checkpoint kinase 2 (CHK2) is a critical negative regulator of androgen receptor (AR) transcriptional activity, prostate cancer (PCa) cell growth, and androgen sensitivity." (PMID 32579110, 2020). "Among candidate prostate cancer genes, PV frequencies were highest for BRCA2 (3.8%), ATM (2.7%), and CHEK2 (2.5%)." (PMID 32439974, 2020). "Another UK Biobank based study reported similar results on the same cancers with minor differences in the monogenic gene selection (BRCA1 and CHEK2 were not used for prostate cancer) and PRS was divided by population tertiles." (PMID 40016794, 2025). "In prostate cancer, the population without pathogenic variants in BRCA1/2, CHEK2, ATM and HOXB13E accounted for 98.0% of individuals and 95.8% of cases." (PMID 40016794, 2025). "Apparently, those with BRCA2 mutations respond better to PARP inhibitors as compared to the prostate cancer patients with ATM and CHEK2 alterations; nevertheless, the same correlation with higher genomic scarring composite scores has been revealed in the respective DDR gene mutations." (PMID 36010882, 2022). "Moreover, there is good evidence from prostate cancer that the PARPi olaparib is effective in tumours with alterations in RAD51C, RAD51D, CHEK2, PALB2, RAD54L, and BARD1." (PMID 34680387, 2021). "Mutations in DNA damage repair pathway genes, including BRCA2 and CHEK2 have also been reported in pancreatic NET48 and may promote tumour sensitivity to LuTate, as reported in BRCA2 mutant prostate cancer treated with Lu-177 PSMA therapy." (PMID 32576907, 2020). "Importantly, the HRR abnormalities are observed in 31% of advanced prostate cancers and include: BRCA2 (9.8%), CDK12 (5.6%), ATM (5.2%), CHEK2 (1.8%), BRCA1 (1.4%) FANCA (1.3%), and ATR (1.1%)." (PMID 31366128, 2019). "There were 5271 prostate cancer patients included with 18 (0.3%) having germline BRCA1 alterations, 139 (2.6%) with BRCA2 alterations, 49 (0.9%) with germline ATM alterations, 15 (0.3%) with germline PALB2 alterations, and 27 (0.5%) with germline CHEK2 alterations." (PMID 40361359, 2025). "While prostate cancer is an expected phenotype of CHEK2, brain cancer is not." (PMID 41465149, 2025). "Finally, the low penetrance CHEK2 I157T alteration identified via germline testing in a prostate cancer patient was absent from the tumor CGP test, which had sufficient coverage in this region of the CHEK2 gene." (PMID 35962742, 2023).
colorectal cancer (84 papers, 2005 to 2025). A primary or metastatic malignant neoplasm that affects the colon or rectum. "Some studies have found a slight association between certain CHEK2 mutations and an increased risk of colorectal cancer." (PMID 40869938, 2025). "On the other hand, the variant in the CHEK2 gene would be related to the patient's colorectal cancer." (PMID 40177144, 2025). "Patients with CHEK2 P/LP variants in our sample population experienced a relatively early onset of colorectal cancer." (PMID 40869938, 2025). "Running against this, activation of CHEK2 has recently been shown to confer resistance to oxaliplatin treatment in colorectal cancer and overexpression of CHEK2 was linked to worse survival in adrenocortical carcinoma." (PMID 41152984, 2025). "In this context, we present a case of a patient exhibiting polyposis coli, colorectal cancer, atypical leukemia and cerebral tumour who carries pathogenic variants in the CHEK2 and JAK2 genes and one variant of uncertain significance (VUS) in APC." (PMID 40177144, 2025). "Beyond the well-established BRCA1/2 and Lynch syndrome genes, large panels can identify pathogenic variants in other moderate-to-high penetrance genes, such as PALB2 and CHEK2, which are implicated in both breast and colorectal cancer risks." (PMID 41378290, 2025). "Germline mutations in CHEK2 have been primarily associated with predisposition to breast, prostate and colorectal cancers but there is increasing evidence for an association with RCC with an approximately two-fold increased lifetime risk." (PMID 38802529, 2024). "In this study, we found an increased risk of colorectal cancer and haematological cancers for women from CHEK2 c.1100delC families." (PMID 39384226, 2024). "In contrast, current National Comprehensive Cancer Network (NCCN) guidelines recommend colorectal cancer screening for individuals who carry CHEK2 P/LP variants." (PMID 39371170, 2024). "For example, DNA damage response mechanisms involving the cell cycle kinases ataxia telangiectasia mutated (ATM) and checkpoint kinase 2 (CHK2) are known to contribute to the development of colorectal cancer." (PMID 37631237, 2023). "As a result, healthy carriers of CHEK2 pathogenic mutations were offered breast and colorectal cancer surveillance in accordance with NCCN and AIOM (Italian Association of Medical Oncology) while also taking their family history into account." (PMID 38136276, 2023). "A CHEK2 c.1100delC (likely) pathogenic variant is associated with an increased risk of breast, prostate and colorectal cancer and therefore risk-specific screening will be offered." (PMID 35101071, 2022). "For example, both male BC susceptibility and colorectal cancer susceptibility are associated with pathogenic variants in the CHEK2 gene." (PMID 36115878, 2022). "In the cohort, 13 variants in CHEK2 were identified, of which, 9 were found in patients diagnosed with colorectal cancer." (PMID 36232851, 2022). "CHEK2 is a susceptibility gene for several types of cancer such as breast, ovarian, and colorectal cancer, among others." (PMID 36232851, 2022). "Germline testing for selected CHEK2 mutations has been included in most breast cancer, colorectal cancer, and pan-cancer panels from major commercial genetic testing laboratories." (PMID 35267514, 2022). "Loss of kinase function caused by mutations in the CHEK2 gene has been linked with Li–Fraumeni syndrome, sarcomas, breast, and colorectal cancer, brain, thyroid, lung, ovary, bladder, and prostate and kidney tumors." (PMID 32570972, 2020). "With this in mind, we have also reviewed the clinical importance of germline CHEK2 mutations in patients with breast, prostate, kidney, papillary thyroid, and colorectal cancers." (PMID 33322746, 2020). "Subsequent NGS of 450 early-onset colorectal cancer patients from Ohio utilizing a 25-gene panel identified only one CHEK2 pathogenic mutation; however, the authors reported another 18 CHEK2 variants as VUS (including six p.I157T)." (PMID 33322746, 2020).
colorectal cancer (continued). "Significant associations of the CHEK2 I157T variant with colorectal cancer susceptibility were found (OR = 1.67, 95% CI = 1.24–2.26, p = 0.0008)." (PMID 32570972, 2020). "The cancer spectrum in families of carriers of pathogenic or likely pathogenic CHEK2 variants based on functional assays, was consistent with the literature including breast, early onset breast, prostate, and colorectal cancers." (PMID 31780696, 2019). "A particularly high frequency of the CHEK2 1100delC allele has been reported in families with hereditary breast and colorectal cancer where 10/55 Dutch families (18%) carried the mutation." (PMID 16539695, 2006). "One CHEK2-deficient cancer, a colorectal cancer (CRC), showed MSI." (PMID 38848470, 2024). "Until then, intensified surveillance may be considered for carriers of CHEK2 pathogenic mutations from families with multiple appearances of colorectal cancer." (PMID 33322746, 2020). "However, a germline protein-truncating variant of CHEK2, 1100delC, was first identified in a patient with breast and colorectal cancer from a family with Li Fraumeni-like syndrome." (PMID 15700044, 2005). "However, the role of the CHEK2 gene in colorectal cancer predisposition remains controversial." (PMID 40869938, 2025). "However, the role of the CHEK2 gene in predisposition to colorectal cancer remains controversial." (PMID 40869938, 2025). "Nevertheless, the fact that both patients in our cohort with P/LP variants in CHEK2 are younger than the mean age of diagnosis in this cohort (67 years) and both have a family history of the disease suggests that CHEK2 may predispose the Panamanian population to colorectal cancer." (PMID 40869938, 2025). "However, the prevalence of CHEK2 mutation is relatively low in colorectal cancer." (PMID 35530355, 2022). "Following an initial report of a family with a CHEK2 germline mutation expressing an increased cancer incidence resembling the Li-Fraumeni syndrome, recent studies have revealed the more common CHEK2 mutations to be associated with a moderately increased risk of breast and colorectal cancers." (PMID 18725978, 2008). "Separately, in colorectal cancer, the tumor-suppressive lncRNA LINC00982 encodes PRDM16-DT, which interacts with HNRNPA2B1 to suppress CHEK2 exon skipping." (PMID 41304936, 2025). "Among individuals with mutations in CHEK2, BRCA2, PMS2, and APC, a high proportion reported a family history of breast, ovarian, prostate, pancreatic, or colorectal cancer (8 out of 11 considered patients)." (PMID 41294693, 2025). "METTL1 promotes colorectal cancer cell proliferation by attenuating checkpoint kinase 2 (CHEK2)‐induced G1/S phase arrest." (PMID 39979979, 2025). "First, in terms of promoting tumorigenesis, METTL1 promotes colorectal cancer cell proliferation and G1/S translation by inhibiting checkpoint kinase 2 (CHEK2) expression." (PMID 39850560, 2024). "For breast and colorectal cancers (n = 731), PVs were most frequent in CHEK2 excluding I157T (2.2%, 95% CI 1.4–3.5%), ATM (1.2%, 95% CI 0.6–2.4%), MLH1 (0.8%, 95% CI 0.3–1.9%), and PMS2 (0.7%, 95% CI 0.3–1.7%)." (PMID 36856935, 2023). "Kaplan–Meier analysis showed that high KLC4 and low CHEK2 expression resulted in significantly lower survival rates for patients with lung and colorectal cancer." (PMID 32457423, 2020). "There are limited guidelines for screening and prevention of CHEK2-related breast and colorectal cancers." (PMID 32570972, 2020).
colorectal cancer (continued). "Our findings are in line with previous studies that exclude CHEK2 1100delC as a major contributor to the breast and colorectal cancer phenotype." (PMID 16539695, 2006). "CHEK2 1100delC has been reported in 18% of Hereditary Breast and Colorectal Cancer families from the Netherlands." (PMID 15700044, 2005). "This suggests that the CHEK2 gene may play a role in cases of early-onset colorectal cancer in our population." (PMID 40869938, 2025). "For instance, the 2024 National Comprehensive Cancer Network (NCCN) guidelines state that CHEK2 variants are not linked to an elevated risk of colorectal cancer." (PMID 40869938, 2025). "Specifically, in colorectal cancer, there is not yet consistent evidence that CHEK2 variants contribute greatly to cancer predisposition, although a low-to-moderate risk has been found for c.1100delC and a low risk for p.I157T carriers." (PMID 40177144, 2025). "The published data do not provide consistent evidence that germline CHEK2 alterations substantially contribute to increased colorectal cancer risk." (PMID 33322746, 2020). "However, the possibility that CHEK2, due to its role in cell cycle regulation, may influence the risk of other familial cancers in the French Canadian population, such as prostate, colon, ovarian or colorectal cancer, and would thus be an informative population for such future investigations." (PMID 18706089, 2008). "We utilized the Southern Sweden population-based cancer registry to identify women with double primary breast and colorectal cancer and sequenced tumor material in order to assess the contribution of the CHEK2 1100delC to the development of such metachronous tumors." (PMID 16539695, 2006). "In summary, our data suggest that the CHEK2 1100delC is not a major cause of double primary breast and colorectal cancer in Sweden, which suggests that this patient group should not routinely be screened for the CHEK2 1100delC variant." (PMID 16539695, 2006). "However, recent wide cohort studies showed no increased risk of colorectal cancer in patients with CHEK2 variations." (PMID 39594831, 2024). "The most frequent were PV in CHEK2 (in three patients from PDAC families and in one colorectal cancer family)." (PMID 34503238, 2021). "Additional studies have shown that increases in reactive oxygen species following SOD1 (Superoxide Dismutase 1) silencing and inhibition induces SL killing in colorectal cancer cells harboring defects in established CIN genes, like RAD54B, BLM, and CHEK2." (PMID 29104272, 2017). "In summary, although additional confirmation is needed for breast, prostate and colorectal cancers, genomic ascertainment showed generally lower (or non-significant) risk than previously reported for All, PTV and PMV in CHEK2." (PMID 39371170, 2024). "Different NGS studies have reported that up to 18% of patients under 50 years old, diagnosed with colorectal cancer, have a PV in genes that are not traditionally associated with this neoplasm such as ATM, CHEK2, and BRCA1/2." (PMID 36232851, 2022). "For CHEK2 GPV carriers unaffected by colorectal cancer, high-quality colonoscopy is proposed every 5 years starting at 40 years or 10 years prior to the first-degree relative’s age with colorectal cancer if the carriers have a first-degree relative with colorectal cancer." (PMID 35806485, 2022). "Of the two individuals who carried two DV in genes other than MUTYH, one was affected with colorectal cancer and carried a DV in CHEK2 and PALB2, while the second was not personally affected with cancer but did have a family history of breast and gastric cancer and carried DV in PMS2 and CDH1 genes." (PMID 29308099, 2018).
colorectal cancer (continued). "In summary, although additional confirmation is needed for breast, prostate, and colorectal cancers, genomic ascertainment showed generally lower (or not significant) risk than previously reported for individuals in the all-variant, PTV, and PMV groups in CHEK2 variants." (PMID 41396600, 2025). "For CHEK2 GPV carriers, there is no specific screening strategy for cancers other than breast and colorectal cancer." (PMID 35806485, 2022).
colon carcinoma (56 papers, 2002 to 2025). "CHEK2 DNA repair gene pathogenic mutations also account for a significant amount of breast and colon cancer." (PMID 38136308, 2023). "Although it was well known that CHEK2 mutations are associated with breast and colon cancers, within the last few years, it has been recognized to also be associated with PNETs." (PMID 36440216, 2022). "Six of our BC patients carrying a CHEK2 pathogenic mutation were also diagnosed with thyroid carcinoma, acute myeloid leukemia, colon cancer, malignant melanoma, or uterine endometrial carcinoma." (PMID 33919281, 2021). "Targeted NGS revealed that CHEK2 was the second most frequently altered gene (following heterozygous MUTYH) in the Ambry Genetics ColoNext panel with germline CHEK2 mutations found in 8/586 colon cancer patients." (PMID 33322746, 2020). "These four CHEK2 variations synergistically interacted (crude ORinteraction = 1.16) with CDKN1B rs2066827 encoding p.Val109Gly in colon cancer risk." (PMID 27588484, 2016). "Among the four CHEK2 polymorphisms associated with colon cancer risk, three variants (del5395, 1100delC and c.444+1G>A) produce truncated proteins, and one (I157T) is a missense mutant." (PMID 27588484, 2016). "CHEK2 mutations confer substantial risks for breast, prostate and colon cancer, but the cancer risk appears to vary between and within populations." (PMID 19401704, 2009). "Ours is the first study to show that, among relatives of CHEK2 mutation carriers, the risks of breast, prostate and colon cancer differ dramatically depending on the type of cancer diagnosed in the proband." (PMID 19401704, 2009). "For the cancer susceptibility genes identified in the cohort that are not involved in LS, we found several genes implicated in the hereditary colorectal cancer landscape: APC, MUTYH, POLE, POLD1, and BLM, as well as genes resulting in an increased risk of colon cancer as CHEK2." (PMID 36232851, 2022). "CHEK2 pathogenic variants are also implicated in a 1.5–2 fold increase in colon cancer risk." (PMID 33507482, 2021). "Using this data, we are able to estimate the cumulative incidence of all cancers in the first-degree relatives of the carriers, and to compare the risks by specific CHEK2 mutation, and by the disease status of the index case (breast or prostate or colon cancer)." (PMID 19401704, 2009). "In addition, some authors have suggested an association with colon cancer for CHEK2 mutations." (PMID 34204722, 2021). "Among the PGVs identified in patients with early-onset colon cancer, CHEK2 (OMIM 604373) found in 1 patient was the only PGV with a known yet weak association with risk of CRC." (PMID 37462969, 2023). "On the other hand, CHEK2 families presented a recurrence of colon cancer (35.3% of cases), prostate tumors (23.5%) and kidney/bladder cancers (23.5%)." (PMID 33919281, 2021). "In vitro co-culturing HCT-116 and HT29 colon cancer cells with wild type (WT) F. nucleatum increased cell proliferation and DNA damage induced by fadA mediated activation of checkpoint kinase 2 (CHK2)." (PMID 34708063, 2021). "For example, Cherfas found that gene CHEK2 is closely related to the occurrence and development of colon cancer." (PMID 29670664, 2018). "However, she also received counseling for management of risk for other malignancies including colon cancer, pancreatic cancer, and melanoma based on the presence of concurrent pathogenic mutations in BRCA2 and CHEK2." (PMID 33507482, 2021). "No other cases of colon cancer were described in the other families of patients with the CHEK2 mutation." (PMID 34204722, 2021). "Similarly, five genes including TOP2A, REL, SHH, ROS1, and CHEK2 in colon cancer gene network and three genes including RBL1, MAPK9, and PIK3CA in adenocarcinoma of lung gene network are selected." (PMID 29670664, 2018).
colon carcinoma (continued). "Among the top 10 regulatory kinases, only CHEK2 and nemo-like kinase (NLK) had a significant impact on outcome in patients with rectal cancer; of note, none of these kinases had a significant influence on the outcome of patients with colon cancer." (PMID 36164349, 2022).